MSX2 (msh homeobox 2)
Diseases named in the same sentence as MSX2 in open-access papers (continued):
Sharing a sentence is not in itself a finding about the gene and the disease.
osteopetrosis (2 papers, 2013 to 2015). Osteopetrosis, also known as marble bone disease, is a descriptive term that refers to a group of rare, heritable disorders of the skeleton characterized by increased bone density on radiographs. "Although compensation for RANKL loss of function could have potential as a therapy for osteopetrosis, but in Msx2−/− mice, this approach via RANK overexpression in monocyte-derived lineages, amplified latent epithelial tumor development in the peculiar continuously growing incisor." (PMID 24278237, 2013). "In order to elucidate the role of such an osteopetrosis in the Msx2−/− mouse dental phenotype, a bone resorption rescue was performed by mating Msx2−/− mice with a transgenic mouse line overexpressing Rank (Tnfrsf11a)." (PMID 24278237, 2013). "However, the role of osteopetrosis in the multifaceted dental phenotypes observed in Msx2−/− mice is unclear." (PMID 24278237, 2013). "In addition, Msx2−/− mice display dentinogenesis imperfecta and regional and graded osteopetrosis from the first to the third molar, with inclusion of the mandibular third molar." (PMID 24278237, 2013). "Therefore, in order to investigate the importance of osteopetrosis in Msx2−/− mouse dental defects, we developed a strategy to rescue bone resorption by overexpressing RANK in osteoclast precursors of Msx2−/− mice." (PMID 24278237, 2013). "Previous studies have suggested that osteopetrosis in Msx2−/− mutants could have two nonexclusive origins." (PMID 24278237, 2013). "In conclusion, rescuing bone resorption in Msx2−/− mice by overexpressing RANK in the osteoclastic lineage allowed for the correction of a substantial portion of the molar abnormalities, most likely by counteracting the decrease in RANKL expression, which is correlated with Msx2−/− osteopetrosis." (PMID 24278237, 2013).
osteosarcoma (2 papers, 2012 to 2022). A usually aggressive malignant bone-forming mesenchymal neoplasm, predominantly affecting adolescents and young adults. "In order to test whether FOXC1could regulate the expression of endogenous MSX2, we over expressed FOXC1 in U2OS human osteosarcoma cells and measured MSX2 mRNA expression by qRT-PCR." (PMID 23145080, 2012).
prostate carcinoma (2 papers, 2017). A carcinoma that arises from epithelial cells of the prostate gland. "In prostate cancer, the expression of MSX2 was upregulated in the tumors with bone metastasis." (PMID 28286778, 2017). "MSX2 was considered to be an independent prognostic factor in advanced prostate carcinoma." (PMID 28286778, 2017).
Saethre-Chotzen syndrome (2 papers, 2016 to 2022). Saethre-Chotzen syndrome (SCS) is an inherited craniosynostosis syndrome characterized by unilateral or bilateral coronal synostosis, facial asymmetry, ptosis, strabismus and small ears with prominent crus, among other less common manifestations. "In the mouse models for Saethre-Chotzen syndrome (single or compound Msx2-Twist mutants), osteoblastic differentiation markers were reduced by E12.5, while proliferation is not reduced until E14.5." (PMID 26886780, 2016).
adenoma (1 paper, 2012). A neoplasm arising from the epithelium. "Consistent with the results of QRT-PCR, the immunoreactivity of MSX2 was frequently found in borderline IPMN (3/5, 60%), carcinoma of IPMN (12/19, 63.2%), and invasive carcinoma derived from IPMN (5/5, 100%), while its expression was seen in only one of 16 adenoma of IPMN tissues." (PMID 23162473, 2012).
ameloblastoma (1 paper, 2013). The most common odontogenic tumor, arising from the epithelial component of the embryonic tooth and usually affecting the molar-ramus region of the mandible or maxilla. "Our finding that Msx2 is downregulated by Ambn is supported by earlier studies reporting upregulation of Msx2 in ameloblasts from Ambn deficient mice and downregulation of MSX2 in human ameloblastoma cells overexpressing AMBN." (PMID 23593111, 2013).
amelogenesis imperfecta (1 paper, 2020). Amelogenesis imperfecta (AI) represents a group of developmental conditions affecting the structure and clinical appearance of the enamel of all or nearly all the teeth in a more or less equal manner, and which may be associated with morphologic or biochemical changes elsewhere in the body. "Msx2 and Sp6 mouse mutants, exhibit similar amelogenesis defects, namely enamel hypoplasia, while humans with amelogenesis imperfecta (AI) carry mutations in the human homologues of MSX2 or SP6 genes." (PMID 33192593, 2020). "In a case of syndromic amelogenesis imperfecta (AI) sequence analysis of the human homolog of MSX2 gene identified a missense mutation of T447C, further indicating the important role of Msx2 during amelogenesis." (PMID 33192593, 2020).
Apert syndrome (1 paper, 2009). Apert syndrome (AS) is a frequent form of acrocephalosyndactyly, a group of inherited congenital malformation disorders, characterized by craniosynostosis, midface hypoplasia, and finger and toe anomalies and/or syndactyly. "In the last century, we have advanced from the first clinical description of Apert syndrome to the description of the FGFR, TWIST and MSX2 mutations." (PMID 20108486, 2009).
asthma (1 paper, 2009). "To determine the mechanisms underlying the progression from AD to asthma, we first generated animals that lacked Notch signaling in a portion of their skin surfaces by embryonic removal of RBP-j from keratinocytes using the Msx2-Cre transgene (Msx2-Cre/+;RBP-jflox/flox or RBP-jCKO)." (PMID 19557146, 2009).
bladder cancer (1 paper, 2025). "These loci included 14 previously reported bladder cancer-associated genes (eg, GSTM1 and NAT2) and 3 novel loci near MSX2, RAPGEF5, and MIPOL1 genes." (PMID 39898788, 2025).
choroidal melanoma (1 paper, 2022). Malignant tumor of melanocytes of the choroid. "In choroidal melanoma, it is interesting to note that the expression patterns of MSX1 and MSX2 vary between tumor types." (PMID 36012688, 2022).
chronic pancreatitis (1 paper, 2012). A chronic inflammatory process causing damage and fibrosis of the pancreatic parenchyma. "In this review, we focus on the involvement of MSX2 in the enhancement of malignant behavior in PDAC and IPMN, and further highlight the clinical approach to differentiate PDAC from chronic pancreatitis by evaluating MSX2 expression level." (PMID 23162473, 2012).
craniofacial clefts (1 paper, 2022). "Some of these proteins like Homeobox Protein BarH-like 1 (BARX1), Distal-Less Homeobox 4 (DLX4), Forkhead Box E1 (FOXE1), Homeobox Protein Hox-B3 (HOXB3), and Muscle Segment Homeobox 2 (MSX2) have been associated with the formation of craniofacial clefts." (PMID 37733420, 2022).
enamel hypoplasia (1 paper, 2020). "Both, Msx2 and Sp6 mouse mutants, exhibit enamel hypoplasia, while humans with AI carry mutations in the human homologues of MSX2 or SP6 genes." (PMID 33192593, 2020).
endometrial cancer (1 paper, 2018). Primary or metastatic malignant neoplasm involving the endometrium (mucous membrane that lines the endometrial cavity). "Furthermore, the expression of estrogen-responsive genes KIAA1324, MLPH, MSX2, SPDEF, TFF3, and PIGR were all significantly up-regulated in CTCF-altered endometrial cancers (p = 0.0004, 0.0007, 0.0032, 0.0009, 0.0122, and 0.0028 respectively)." (PMID 30513694, 2018).
epithelioid melanoma (1 paper, 2022). "MSX2-positive cells were observed in the eye section of an 8-week-old human embryo in the retina and choroid in retinoblastoma (remaining retina, choroid, and tumor tissue), in myxoid in tumor tissue only, and in epithelioid melanoma in the retina and choroid." (PMID 36012688, 2022). "MSX2 was also expressed in the retina and choroid of epithelioid melanoma, with significantly higher expression in the retina but not in the retina or choroid of spindle melanoma or myxoid melanoma." (PMID 36012688, 2022).
female infertility (1 paper, 2012). Diminished or absent ability of a female to achieve conception. "Conditional ablation of both Msx1 and Msx2 in the uterus resulted in female infertility due to a failure in implantation." (PMID 22383889, 2012). "Ablation of uterine Msx1 and Msx2 leads to female infertility." (PMID 22383889, 2012).
Hyperinsulinemia (1 paper, 2025). An increased concentration of insulin in the blood. "In the context of how hyperinsulinemia promotes vascular calcification, earlier studies have shown that in insulin-resistant ob/ob mice, while Msx2 is important for osteochondrogenic differentiation of VSMC, Msx2 signaling alone may not be sufficient for vascular calcification." (PMID 40940776, 2025).
Hyperkeratosis (1 paper, 2022). Hyperkeratosis is a histopathological term defining a thickened stratum corneum and may be present in many different skin conditions, with many possible overlaps. "Histological analysis showed that overexpression of the Msx2 gene in mice resulted in thickening of the basal epidermal and hyperkeratosis." (PMID 36510127, 2022).
nodular melanomas (1 paper, 2011). "Subanalyses including superficially spreading and nodular melanomas only showed a significant correlation of cytoplasmic MSX2 positivity with both recurrence-free (P=0.015) and overall survival (P=0.024)." (PMID 21730974, 2011).
orofacial cleft (1 paper, 2022). A disorder of facial skeleton that is characterized by cleft lip and/or cleft palate that result in feeding, speech and hearing problems caused by failures during development. "MSX2 has been associated with the formation of orofacial clefts." (PMID 37733420, 2022). "This implies the possible role of MSX2 in formation of multiple orofacial cleft types." (PMID 37733420, 2022).
parietal foramina (1 paper, 2009). "The collection of human MSX2 mutations (reported on OMIM, *123101) presently consists mostly of loss-of-function mutations (i.e., premature stop codons), homeodomain missense mutations, or frameshift mutations that disrupt/prevent DNA binding and result in parietal foramina (OMIM #168500)." (PMID 19154605, 2009).
partial epilepsy (1 paper, 2020). "In the present work, we also identified variants in MSX2 in four patients with NDD including one with a truncation variant (p.A173fs) showing partial epilepsy as well." (PMID 32530565, 2020).
periodontitis (1 paper, 2021). An acute or chronic inflammatory process that affects the tissues that surround and support the teeth. "Alveolar bone necrosis is induced by experimental periodontitis in Msx2 mutant mice." (PMID 34041852, 2021).
pyometra (1 paper, 2009). "The strong downregulation of homeobox genes in dogs afflicted with pyometra was also verified by qPCR analysis, as shown for MSX2 and HOXA6." (PMID 19956711, 2009).
Retinal dystrophy (1 paper, 2026). Retinal dystrophy is an abnormality of the retina associated with a hereditary process. "Integrated analysis of RNA-seq data from both Gm20541 and Msx2 mutant retinas indicated that ZNF124 is essential for maintaining normal retinal function by regulating Msx2 transcription, which in turn controls the expression of murine homologues of retinal dystrophy genes Rs1, Pde6g, and Pdc." (PMID 41708596, 2026).
retinoblastoma (1 paper, 2022). A malignant tumor that originates in the nuclear layer of the retina. "In addition, retinoblastoma showed moderate expression of MSX2, which was highest in the retina and lowest in the choroid." (PMID 36012688, 2022). "MSX1 and MSX2 expression was similar in the developing eye and retinoblastoma, whereas it was absent in the postnatal eye." (PMID 36012688, 2022). "The expression patterns of MSX1 and MSX2 were similar in 8-week human embryo and retinoblastoma, whereas both were absent in postnatal human eye." (PMID 36012688, 2022).
sirenomelia (1 paper, 2018). Sirenomelia is a rare, genetic, developmental defect during embryogenesis disorder characterized by fusion of the lower limbs and associated with some degree of lower extremity reduction and persistent vitelline artery. "The MR26F8 mice had both striking craniofacial defects as well as limb defects including sirenomelia and post-axial polydactyly, the latter phenotypes consistent with the expression of the Msx2-Cre transgene in the limb bud ectoderm." (PMID 29752281, 2018).
tumor (22 papers, 2010 to 2025). "The Chi-squared test showed that high MSX2 mRNA expression was associated with tumor locus (P = 0.025), tumor size (P = 0.040), clinical stage (P < 0.001), tumor invasion (P < 0.001), lymphatic metastasis (P = 0.01), and distant metastasis (P = 0.033)." (PMID 28286778, 2017). "Cytoplasmic Msx2 expression was associated with low grade tumours (P = 0.012) and Ki67 negativity (P = 0.018)." (PMID 20682066, 2010). "Cytoplasmic Msx2 expression was associated with low-grade tumours (P = 0.012) and low expression of Ki67 (proliferation-related Ki-67 antigen) (P = 0.018)." (PMID 20682066, 2010). "Nuclear Msx2 expression was associated with low-grade (P = 0.015), ER-positive (P = 0.038) tumours, low Ki67 expression (P = 0.005), and increased nuclear cyclin D1 expression (P = 0.037)." (PMID 20682066, 2010). "A study of 32 pancreatic adenocarcinomas demonstrated an association between Msx2 expression and high tumour grade and vascular invasion." (PMID 20682066, 2010). "Owing to core loss, it was possible to evaluate Msx2 protein expression in 281 tumours (55%) of the 512 tumours represented on the TMA." (PMID 20682066, 2010). "Survival analysis of these tumours revealed that increased expression of Msx2 mRNA was associated with good prognosis (P = 0.011)." (PMID 20682066, 2010). "Since IPMN, like PDAC, harbors frequent K-ras mutations, the association of MSX2 expression with the tumor grade or clinicopathological features was examined in IPMN tissues to determine whether this gene could be involved in the process of benign-to-malignant progression in IPMN." (PMID 23162473, 2012). "In cardiac myxoma, MSX2’s role depends on the tumor microenvironment, potentially promoting a progenitor-like state in advanced cases." (PMID 38110859, 2023). "MSX2 was found to be highly expressed in CRC tumor tissues, cell proliferation and invasion were suppressed, cell cycle arrest and apoptosis were promoted, and Akt phosphorylation was inactivated when MSX2 expression was knocked down." (PMID 34698109, 2021). "Since the median ΔCt of MSX2 in tumor tissues was 8.50, the 136 patients were divided into high and low expression groups according to ΔCt value less than 8.5 or greater than 8.5, respectively." (PMID 28286778, 2017). "Compared with adjacent tissues, the expression of MSX2 was higher in tumor tissues in both mRNA and protein levels (P < 0.01)." (PMID 28286778, 2017). "An IHC analysis with another 10 pairs of sample was further performed to validate the expression of MSX2 in colorectal tissue, which showed a stronger expression in tumor tissues compared with the corresponding adjacent tissues in 7 pairs." (PMID 28286778, 2017). "Another compliment experiment with 10 pairs of samples by IHC showed that 7 of which had significant high expression in tumor tissues, which further confirmed high expression of MSX2 protein in CRC." (PMID 28286778, 2017). "Collectively, these results indicated that MSX2 expression was significantly elevated in CRC tumor tissues compared with adjacent tissues." (PMID 28286778, 2017). "We observed a higher expression of MSX2 in CRC tumor tissues than adjacent tissues in mRNA and protein level, which correlated with the malignancy of CRC." (PMID 28286778, 2017). "Since MSX2 generally plays a regulatory role in the protein level, we evaluated the protein expression of tumor tissues with increased mRNA expression using western blotting." (PMID 28286778, 2017). "Consistently, western blotting confirmed the upregulation of MSX2 in tumor tissues at protein level (P < 0.01, n = 10)." (PMID 28286778, 2017). "Chi-squared test analysis indicated that MSX2 expression was related to tumor size (P = 0.04), tumor locus (P = 0.025), clinical stage (P < 0.001), tumor invasion (P = 0.003), lymphatic metastasis (P = 0.01), and distant metastasis (P = 0.033)." (PMID 28286778, 2017).
tumor (continued). "With regard to studies in tumour model systems, we recently showed induction of apoptosis in both human breast immortalised and transformed cell lines in response to MSX2 over-expression." (PMID 21730974, 2011). "This was confirmed at the protein level, where tissue microarray (TMA)-based analysis of 281 invasive breast carcinomas showed a significant correlation of cytoplasmic MSX2 expression with low-grade tumours and prolonged patient survival." (PMID 21730974, 2011). "Similar to MSX2, they have been ascribed both oncogenic and tumour suppressor activities, depending on their cell type or tissue context." (PMID 21730974, 2011). "Evaluation of Msx2 protein expression on a TMA revealed that Msx2 was detectable in both tumour cell nuclei and cytoplasm." (PMID 20682066, 2010). "Tumour-specific nuclear and cytoplasmic expression of Msx2 protein was evident, with levels of Msx2 in these subcellular compartments being scored separately." (PMID 20682066, 2010). "On the basis of this analysis, 168 tumours (59.8%) were classified as expressing low levels of cytoplasmic Msx2, and 113 tumours (40.2%) were classified as expressing high cytoplasmic Msx2." (PMID 20682066, 2010). "Nuclear Msx2 correlated with low-grade tumours (P = 0.015), estrogen receptor positivity (P = 0.038), low Ki67 (P = 0.005) and high cyclin D1 expression (P = 0.037)." (PMID 20682066, 2010). "Cytoplasmic Msx2 expression was an independent predictor of prolonged OS (HR 0.58; 95% CI 0.36-0.93; P = 0.023), along with tumour grade (HR 1.78; 95% CI 1.06-2.99; P = 0.028) and nodal status (HR 3.06; 95% CI 1.95-4.80; P < 0.001)." (PMID 20682066, 2010). "The varying effect of Msx2 expression in different tumour types also suggests a cell type-specific effect." (PMID 20682066, 2010). "MSX2 represses tumor stem cell phenotypes by SOX2 dysregulations in SCC." (PMID 38110859, 2023). "FOXA1 and MSX2 were experimentally validated to induce the EMT process and tumor metastasis in other cancers, indicating that FOXA1 and MSX2 may be critical drivers in tumor metastasis of TNBC." (PMID 36291687, 2022). "In addition, FOXA1 and MSX2 were up-regulated in tumor samples compared to normal samples in TNBC patients and were experimentally validated to induce the EMT process and tumor metastasis." (PMID 36291687, 2022). "Increasing evidence indicated that MSX2 was involved in the development of tumor." (PMID 28286778, 2017). "Similarly, 122 tumours (43.4%) were classified as expressing low nuclear Msx2, and 159 tumours (56.6%) were classified as expressing high nuclear Msx2." (PMID 20682066, 2010). "Therefore, our hypothesis is that MSX2 may promote the distal metastasis of the tumor cells via vascular calcification." (PMID 28286778, 2017). "Therefore, although the involvement of MSX2 in tumor invasion was consistently observed in several kinds of carcinoma, the role of MSX2 in EMT might depend on the tumor species." (PMID 23162473, 2012). "In the metastasis-associated neoplastic cell states, we detected robust expression of neural crest (ZIC1, OLIG3), mesenchymal (MSX2, GDF6), and metastasis-related (DKK2) genes in addition to adrenergic genes (e.g., PHOX2B) that were shared with primary tumor cell states." (PMID 41279557, 2025). "According to nuclear staining, 97 tumours (48.5%) were graded as MSX2 negative, while 103 (51.5%) stained positive." (PMID 21730974, 2011). "For 54 patients (27%), the expression of MSX2 was exclusively cytoplasmic, 76 patients (38%) had both cytoplasmic and nuclear staining, for 27 patients (13.5%) only nuclear MSX2 expression was detectable and 42 tumours (21.5%) did not express MSX2." (PMID 21730974, 2011).